SNORD115-38 (small nucleolar RNA, C/D box 115-38)
Synonyms: HBII-52-38
Gene: Small nucleolar RNA gene on chromosome 15 (25,239,838 to 25,239,919, forward strand). Ensembl gene ENSG00000201907.
Gene Ontology:
Biological process: RNA processing
Cellular component: nucleolus
Homologues: Orthologues: chimpanzee SNORD115 (100% identical), rabbit SNORD115 (94% identical), rabbit SNORD115 (93% identical), rabbit SNORD115 (91% identical), rabbit SNORD115 (90% identical), pig SNORD115 (89% identical), rabbit SNORD115 (89% identical), rabbit SNORD115 (88% identical), rabbit SNORD115 (87% identical), rabbit SNORD115 (85% identical), pig SNORD115 (84% identical), rabbit SNORD115 (84% identical), and 13 more. Paralogues in human: SNORD115-8 (99% identical), SNORD115-11 (98% identical), SNORD115-29 (98% identical), SNORD115-36 (98% identical), SNORD115-43 (98% identical), SNORD115-12 (96% identical), SNORD115-16 (96% identical), SNORD115-22 (96% identical), SNORD115-26 (96% identical), SNORD115-39 (96% identical), SNORD115-44 (96% identical), SNORD115-6 (96% identical), and 37 more.